ENSG00000200377
Synonyms: LOC124900522
Gene: Small nucleolar RNA gene on chromosome 2 (153,446,813 to 153,446,883, reverse strand). Ensembl gene ENSG00000200377.
Gene Ontology:
Biological process: RNA processing
Cellular component: nucleolus
Homologues: Paralogues in human: SNORD56 (82% identical), SNORD56B (82% identical).